MIR4426 (microRNA 4426)
Synonyms: hsa-mir-4426
Gene: MicroRNA gene on chromosome 1 (192,716,328 to 192,716,390, forward strand). Ensembl gene ENSG00000283795.
Diseases named in the same sentence as MIR4426 in open-access papers:
MIR4426 is named in the same sentence as 1 disease in open-access papers, as found by Europe PMC text mining. Sharing a sentence is not in itself a finding about the gene and the disease.
MIR4426 shares sentences with these, for which no sentence is quoted: cancer (1 paper).